MIR3160-1 (microRNA 3160-1)
Synonyms: hsa-mir-3160-1; mir-3160-1
Gene: MicroRNA gene on chromosome 11 (46,451,805 to 46,451,889, reverse strand). Ensembl gene ENSG00000265014.
Homologues: Orthologues: chimpanzee MIR3160-1 (100% identical).